STAT3 (signal transducer and activator of transcription 3)
Diseases named in the same sentence as STAT3 in open-access papers (continued):
Sharing a sentence is not in itself a finding about the gene and the disease.
lung carcinoma (continued). "Our findings demonstrate that although Stat3 is generally growth promoting and in an activated form it can act as an oncogene, it is actually required for gap junctional communication both in nontransformed lung epithelial cells and in certain lung cancer lines that retain extensive GJIC." (PMID 23244248, 2012). "Finally, we delved into the EGFR downstream signaling pathway and observed that several EGFR signaling-related proteins such as p-AKT, p-STAT3, JNK, and p-ERK were decreased upon GLUT1 knockdown, suggesting GLUT1 could activate EGFR signaling pathway in lung cancer." (PMID 38831321, 2024). "In the A549 lung cancer cell line (in which EGF receptors are overexpressed), the phosphorylation levels of ERK1/2, STAT3, and AKT1 were not altered by GTN057 when these cell lines were activated by epidermal growth factor (EGF) stimulation." (PMID 36825580, 2023). "After the knockdown of MRE11 in lung cancer cells, we discovered that IL-6 or the conditional medium of THP-1 cells can induce the mRNA expression of STAT3 downstream genes, including CCL2, in the control cells, but not in MRE11-knockdown lung cancer cells." (PMID 36547079, 2022). "The mRNA expression of lncMALAT1, STAT3, and FUT4 was significantly high in A549/T cells as compared with the non-resistant A549 lung cancer cells." (PMID 35281907, 2022). "As opposed to STAT3, the special AT-rich sequence binding protein 2 (SATB2) transcription factor suppresses G9a expression and mitigates the invasiveness of lung cancer." (PMID 35740522, 2022). "JAK2 is a major upstream nonreceptor tyrosine kinase that activates STAT3 and we investigated the effect of CHK9 on the activation of JAK2 in lung cancer cells." (PMID 32967366, 2020). "In another word, Mcl-1 is the down-stream target of STAT3, but the canonical JAK is not the up-stream kinase of STAT3 in H1299 lung cancer cells." (PMID 31956373, 2020). "We further treated lung cancer cells with IL-6 (10 ng/ml) in the presence of CDK1i or not, and found CDK1i downregulated GP130 and blocked STAT3 phosphorylation as well." (PMID 30931929, 2019). "More importantly, we found that ALDH positive lung cancer cells, marked by ALDH1A1, had lower levels of miR-218 and higher levels of STAT3 signaling than in ALDH negative cells." (PMID 28830450, 2017). "However, it is not known whether STAT3 is also a mediator of BDNF/TrkB signaling in lung cancers." (PMID 27456333, 2016). "To that point, we found that both in vitro and in vivo treatment of GA also suppressed oncogenic Src, an upstream signaling of Stat3, in the TKIR lung cancer but not in the TKIS lung cancer." (PMID 27419630, 2016). "Of note, a number of key pathways activated in lung cancer in never smokers, including EGFR, Akt, MAPK and STAT3, are activated in this mouse model." (PMID 23251519, 2012). "We found that even though prostate cancer cells CWR22Rv-1 and lung cancer cells NCI-H1299 displayed JAK2/STAT3 expression and activating phosphorylation, Cuc IIa still induced apoptosis without clearly inhibiting JAK2/STAT3 phosphorylation." (PMID 21304528, 2011). "As a result, highly increased STAT3 expression enhanced the proliferation, survival, and radioresistance of NSCLC cells, whereas dominant-negative STAT3 resulted in the suppression of human lung cancer cell proliferation and invasive potential." (PMID 36010693, 2022). "Despite the existence of numerous STAT3 inhibitors, none of them have achieved FDA approval for use in clinical trials for lung cancer, indicating that inhibiting STAT3 alone may not be sufficient to eradicate cancer cells." (PMID 35769912, 2022). "Several studies are previously conducted to discover the role of lncRNA MALAT1 in chemoresistance, however, how MALAT1 functions in the context of a therapeutic approach with special prominence to MALAT1/STAT3 and MALAT1/FUT4 axis in paclitaxel-resistant lung cancer is not well-known." (PMID 35281907, 2022).
lung carcinoma (continued). "We observed the significant decrease in the phosphorylation of STAT3 in a time-dependent manner without significant alteration in the levels of STAT3, suggesting that CHK9 induces cytotoxicity by abrogating the STAT3 signaling pathway in lung cancer cells." (PMID 32967366, 2020). "In our study, STAT3 inhibition was effective in the PC9-BM model but not in the A549 model, suggesting that LCN2 expression may serve as a predictive biomarker for STAT3-targeted therapy in lung cancer BM." (PMID 41436606, 2025). "Consequently, treatments based on EGFR inhibition may not be sufficient for the effective treatment of lung-cancer patients with mutant EGFRs and it is necessary to inhibit IL-6/gp130/JAK pathway and further repress STAT3 activity in NSCLC treatment strategy." (PMID 26166037, 2015). "In one study, using lung carcinoma cell line, EGFR inhibition did not block STAT3 phosphorylation and growth arrest, suggesting that upstream pathways, such as JAK and IL6 receptor, may play a role in activating STAT3 and contributing to oncogenesis in lung tumors, even with EGFR activation." (PMID 25763322, 2014). "Finally, we find that inhibition of NOX with VAS2870 did not inhibit STAT3 in lung cancer cells and did not affect their transformed phenotype, suggesting that the transformation properties of oncogenic K-Ras–expressing lung cancer cells rely upon coupling of the AT1-R with STAT3 but not NOX." (PMID 33380422, 2021).
hepatocellular carcinoma (935 papers, 2004 to 2026). A malignant tumor that arises from hepatocytes. "Persistent activation of STAT3 has been implicated in tumor progression and metastasis across a wide spectrum of human malignancies, including hepatocellular carcinoma (HCC), breast, lung, and colorectal cancers." (PMID 40564985, 2025). "FOXM1, GLUT1, and STAT3, other oncogenic transcription factors, are commonly associated with hepatocellular carcinoma, where activated STAT3 is proposed to regulate the expression of FOXM1 and GLUT1." (PMID 40713647, 2025). "Secondly, B7-H3 suppresses T-cell-mediated antitumor immunity by inducing M2-type polarization of tumor-associated macrophages in hepatocellular carcinoma, thereby promoting tumor development through the STAT3 signaling pathway." (PMID 38468228, 2024). "In the NAFLD population, progressive fibrosis was linked to phosphorylation of STAT3, which is associated with an elevated risk for hepatocellular carcinoma (HCC)." (PMID 38751599, 2024). "It has been reported that the high expression of STAT3 causes the occurrence of chemo-resistance and radio-resistance in human hepatocellular carcinoma (HCC) therapy; therefore, it is very important to discover anti-cancer agents that target STAT3." (PMID 37762016, 2023). "The abnormal expression of STAT3 has been found in liver cancer, which is one of the causes of increased hepatocellular carcinoma progression." (PMID 37762016, 2023). "Constitutive activation of the transcription factor STAT3 (signal transducer and activator of transcription 3) contributes to the malignancy of many cancers such as hepatocellular carcinoma (HCC) and is associated with poor prognosis." (PMID 38051779, 2023). "In the present study, the anticancer mechanism of CB-PIC was investigated in human hepatocellular carcinoma cells (HCCs) in association with signal transducer and activator of transcription 3 (STAT3) signaling." (PMID 35742904, 2022). "IL-6 directly acts on hepatocellular carcinoma (HCC) cells to induce the expression of signal transducer and activator of transcription 3 (STAT3) target genes, which encode proteins (including IL-6) and drive tumor proliferation and/or survival." (PMID 35223512, 2022). "Several types of cancer cells, including hepatocellular carcinoma, have been linked to constitutive STAT3 activation, for example, via proliferation, survival, invasion, and angiogenesis." (PMID 36080130, 2022). "In rat hepatoma cells, loss of methylation events in the IL-6/STAT3 promoter was related to higher IL-6 levels and higher proliferation rates." (PMID 34944023, 2021). "Numerous studies have reported that STAT3 activation is associated with a poor prognosis of diverse cancers including, colorectal cancer and hepatocellular carcinoma." (PMID 33658048, 2021). "Hepatocellular carcinoma-associated fibroblasts (CAFs or TAFs), has been shown to induce MDSCs generation through the IL-6/STAT3 axis and stromal cell-derived factor (SDF)-1α secretion." (PMID 31500650, 2019). "Activation of JAK2/STAT3 signaling is associated with enhanced radioresistance of hepatocellular carcinoma cells." (PMID 30551687, 2018). "STAT3 activation is linked to the growth of human hepatocellular carcinoma both in vitro and in vivo, including proliferation, survival, and angiogenesis." (PMID 28743875, 2017). "HCV infection in liver cells causes constitutive activation of STAT3, which plays a central role in chronic hepatitis and often results in liver cirrhosis and hepatocellular carcinoma." (PMID 26199948, 2015). "Hepatocyte-specific STAT3-deficient mice exhibited markedly greater resistance to hepatocellular carcinoma and the tumor sizes were clearly smaller, suggesting that STAT3 is crucial in promoting hepatocellular carcinoma cell proliferation and/or survival." (PMID 25360179, 2014). "In addition, hepatic carcinoma-associated tumor-associated fibroblasts (TAFs) promote MDSC development via the IL-6/STAT3 signaling pathway." (PMID 40918452, 2025).
hepatocellular carcinoma (continued). "It has also been suggested that male-specific susceptibility to hepatocellular carcinoma is due to female protection via estrogen-mediated inhibition of IL-6 expression, as well as direct inhibition of STAT3 via estrogen-mediated expression of the tyrosine phosphatase PTPRO." (PMID 39689092, 2024). "Furthermore, PDIA3 has been implicated in the progression of hepatocellular carcinoma through the modulation of the STAT3 signaling cascade." (PMID 38761176, 2024). "Likewise, by blocking the IL6/STAT3 signaling pathway, morusin caused apoptosis and prevented angiogenesis in hepatocellular cancer cells." (PMID 37228582, 2023). "In particular, HBX-mediated STAT3 activation may be associated with oxidative stress in HBV-associated hepatoma cells." (PMID 35251017, 2022). "Thus, in the present study, the antitumor mechanism of CB-PIC was elucidated in hepatocellular carcinoma cells in association with the Warburg effect and STAT3 signaling." (PMID 35742904, 2022). "Moreover, Spearman’s correlation analysis demonstrated a positive association between STAT3 and hsa_circ_0006916 expression in hepatocellular carcinoma." (PMID 33292166, 2020). "High expression of STAT3 was associated with chemotherapy resistance and immune evasion of hepatocellular carcinoma (HCC) cells." (PMID 38283351, 2023). "TAMs may also release other ILs such as IL-6, IL-17, and IL-23 that can support tumor growth and progression as shown in models of colon cancer and hepatocellular carcinoma, in which tumor progression was associated with activation of the STAT3 signaling pathway." (PMID 38033495, 2023). "Additionally, Stat3 may be involved in polyploidy formation caused by downregulation of endogenous MPHOSPH1 in hepatocellular carcinoma cells." (PMID 34715887, 2021). "For example, silencing of SOCS1 is associated with altered STAT3 activation in the development of hepatocellular carcinoma (HCC)." (PMID 33946612, 2021). "Furthermore, the signal transducer and activator of transcription 3 (STAT3) signaling pathway, which controls these downstream targets, has also been linked to tumor initiation in hepatocellular carcinoma as well as its activator IL-6 cytokine released by M2 macrophages." (PMID 32283687, 2020). "The journal retracts the article titled, “TTF1, in the Form of Nanoparticles, Inhibits Angiogenesis, Cell Migration and Cell Invasion In Vitro and In Vivo in Human Hepatoma through STAT3 Regulation”, cited above." (PMID 41568994, 2026). "This aligns with Bacteroides‐derived acetate activating JAK1/STAT3 to promote M1 polarisation in hepatocellular carcinoma, indicating a conserved immunometabolic axis." (PMID 40739711, 2025). "This study identifies CASP3 and STAT3 as promising therapeutic targets for hepatocellular carcinoma (HCC) using a network pharmacology approach." (PMID 40599803, 2025). "For instance, α-mangostin (α-MGT) was found to inhibit STAT3 activation and exert anti-hepatocellular carcinoma effects, significantly suppressing cell proliferation and inducing apoptosis in various cancer cell lines, including HepG2 and SK-Hep-1." (PMID 40387965, 2025). "For instance, TAMs in hepatocellular carcinoma have been shown to produce IL-6, which activates the STAT3 pathway, promoting the growth of CSCs and tumor progression." (PMID 40083697, 2025). "The other study demonstrates that HILPDA upregulate IL-10 to activate the STAT3 signaling pathway in NK cells, which promotes hepatocellular carcinoma immune evasion and progression." (PMID 40861438, 2025). "STAT3, a transcription factor, is recognized as a promising therapeutic target for hepatocellular carcinoma due to its pivotal role in oncogenesis." (PMID 40599803, 2025).
hepatocellular carcinoma (continued). "This demonstrates that SS-d exerts its anti-hepatoma effects by dose-dependently inhibiting the p-STAT3/C/EBPβ signaling pathway and significantly reducing the expression of cyclooxygenase (COX)-2." (PMID 41011202, 2025). "A recent study revealed that PPVI effectively inhibited the proliferation, migration, and invasion of hepatocellular carcinoma cells by potentially targeting the STAT3 (signal transducer and activator of transcription 3)/GPX4 axis to induce ferroptosis." (PMID 40070365, 2025). "AQP3 promotes stem cell-like properties by regulating AQP3/STAT3/CD133 expression in hepatocellular carcinoma cells." (PMID 39611488, 2025). "Previous work has shown that IL-22 up-regulates CD155 via the STAT3 pathway, thereby reducing sorafenib sensitivity in hepatocellular carcinoma cells and impairing NK-cell-mediated tumor cell lysis." (PMID 41562076, 2025). "GADD45G acts as a negative regulator of the Jak-Stat3 pathway and inhibits HCC by inducing cellular senescence; Deficient PDK4 expression promotes hepatocellular carcinoma cell proliferation, tumorigenicity, motility, and invasiveness." (PMID 40649911, 2025). "The results showed a higher STAT3 and lamin B protein content in NLMs, according to previously obtained results in NLMs purified from liver and hepatoma cells." (PMID 40883422, 2025). "In hepatocellular carcinoma, it has been observed that CAFs can transdifferentiate TIDCs into the rDC phenotype by activating the IL-6-mediated STAT3 pathway." (PMID 40805183, 2025). "Bioinformatics analysis has identified PI3K, transcription factor AP-1 (JUN), and signal transducer and activator of transcription 3 (STAT3) as predictive targets through which SW exerts its anti-tumor effects in hepatocellular carcinoma (HCC)." (PMID 40801607, 2025). "To validate these findings, we conducted a Western blot analysis to examine the levels of p-JAK2/t-JAK2 and p-STAT3/t-STAT3 proteins—pivotal components of the signaling pathway—in hepatocellular carcinoma cells." (PMID 39940837, 2025). "Together, NF-κB and STAT3 cooperate to promote the occurrence and progression of colon, gastric, and hepatocellular carcinoma." (PMID 40841364, 2025). "Circular RNA derived from the mitogen-activated protein kinase 9 (Circ_MAPK9) influences hepatocellular carcinoma progression through silencing miR-642b-3p, thereby promoting the STAT3 and LDHA expression." (PMID 38829380, 2025). "Current research indicates that hepatocellular carcinoma tissue influences the B7-H3/Stat3 signaling pathway by releasing inflammatory stimuli, thereby inducing the polarization of M2-type TAMs." (PMID 40519928, 2025). "Carvacrol (15 mg/kg) combined with sorafenib modulated HIF‐1α/STAT3/FGL1 pathway in a hepatocellular carcinoma (HCC) murine model." (PMID 40964147, 2025). "Icaritin, a bioactive compound sourced from desiccated epimedium stems and leaves, dampens glycolytic processes mediated by GLUT1 in hepatocellular carcinoma (HCC) cells through the impediment of Janus kinase 2 (JAK2)/STAT3 pathway activation." (PMID 40417000, 2025). "HAMP, a gene encoding ferredoxin, can exert cancer suppressor effects in the proliferation and migration of hepatocellular carcinoma cells through the STAT3 pathway." (PMID 40109856, 2025). "Adaptor C21orf58 formed a ternary complex with signal transducer and activator of transcription 3 (STAT3) and Janus kinase 2 (JAK2) to activate wild‐type and constitutively mutated STAT3, enhancing the capacities of malignant growth and sorafenib resistance to hepatocellular carcinoma (HCC) cells." (PMID 38342622, 2024). "NCAPG2 was previously shown to directly interact with STAT3 and activate STAT3 signaling, thus driving hepatocellular carcinoma proliferation and metastasis." (PMID 38166947, 2024). "In hepatocellular carcinoma (HCC) B7-H3 promotes cell invasion by targeting epithelial-mesenchymal transition (EMT) via partially activating JAK2/STAT3/Slug signaling pathway." (PMID 39664380, 2024).